MIF (macrophage migration inhibitory factor)
Diseases named in the same sentence as MIF in open-access papers (continued):
Sharing a sentence is not in itself a finding about the gene and the disease.
breast cancer (continued). "This regulatory dichotomy extends beyond hepatic systems, as evidenced by breast cancer studies showing that macrophage migration inhibitory factor (MIF)-mediated Cav-1 phosphorylation modulates CD11b+ immune cell recruitment." (PMID 40430042, 2025). "MIF levels are significantly elevated in many tumours and promote cell proliferation in prostate tumours, breast cancer, melanoma, colon cancer, and glioma." (PMID 40411322, 2025). "Some studies have found that MIF from breast cancer patients' breast tissue has an anti‐inflammatory effect and can play a cancer‐promoting role in the interaction between cancer cells and the surrounding tissue, leading to a poor prognosis for patients." (PMID 40411322, 2025). "This statement indicates that MIF (Macrophage Migration Inhibitory Factor) is involved in pro-inflammatory processes, as its increased expression in cancer cells and the stroma of breast cancer tissues suggests a role in tumor progression." (PMID 40881277, 2025). "The suggestion of MIF as a prognostic marker for breast cancer highlights its potential involvement in the inflammatory tumor microenvironment, which is often linked to tumor development and progression." (PMID 40881277, 2025). "Inhibition of autophagy in 66cl4 triple negative breast cancer cell line led to increased intracellular ROS levels, which further upregulated MIF expression, potentially through ROS-dependent transcription factors." (PMID 41159021, 2025). "MIF plays a crucial role in breast cancer progression and has been the subject of multiple investigations." (PMID 41159021, 2025). "Researchers have discovered that breast cancer stem cells release MIF, which plays a role in tumour metabolic reprogramming that leads to immune evasion." (PMID 39187937, 2024). "It has been previously reported that EGF is able to induce MIF expression in MCF10CAT breast cancer cells as well as in A431 cervical cancer cells through EGFR/MEK/ERK1/2 signaling pathway." (PMID 38145300, 2024). "Previous studies have shown that intra-tumor hypoxic microenvironment can induce the release of MIF from tumor cells in breast cancer and HNSCC, leading to tumor growth." (PMID 38685050, 2024). "It is known that αvβ5-integrin signaling is mediated by Src tyrosine kinases in various cells, such as endothelial and breast cancer cells, and specific Src kinase family members are involved in the expression of MIF in cardiac muscle cells." (PMID 38145300, 2024). "High expression of MIF has been found in many tumor tissues, such as breast cancer, lung cancer, and melanoma." (PMID 39464891, 2024). "Reducing MIF levels in breast cancer cells increased the presence of cytolytic CD8+ T cells and pro‐inflammatory macrophages inside the TME, while lowering the number of regulatory T cells and tumour‐associated neutrophils." (PMID 39187937, 2024). "Increased dosages of MIF with PRG can inhibit the growth of nPR(+/−) breast cancer cells and ovarian carcinoma cells, and induce apoptosis of these cells." (PMID 36984647, 2023). "Recently, MIF expression has been documented to be upregulated in many cancers and to promote breast cancer and melanoma metastasis by inducing myeloid-derived suppressor cells and TAMs, respectively." (PMID 36797541, 2023). "Breast cancer is associated with a dramatic downregulation of ADRP and FST along with upregulation of the Serpin, LOX-1, COL1A1, and MIF gene expressions, respectively." (PMID 35138531, 2023). "In a parallel context, macrophages present in mammary tumors undergo a substantial reduction of MHC-II expression mediated by tumor-expressed macrophage migration inhibitory factor (MIF)." (PMID 35053449, 2022). "Accumulating research has revealed significant upregulation of MIF in various cancer types, including cervical cancer, breast cancer, prostate cancer, hepatoma, neuroblastoma, colorectal cancer, pancreatic cancer and lymphocytic leukemia." (PMID 35842634, 2022).
breast cancer (continued). "In breast cancer cells, MIF expression promotes autophagy, thereby inhibiting tumorigenesis and enhancing sensitivity to chemotherapeutic drugs." (PMID 35280512, 2022). "Overexpression of macrophage migration inhibitory factor (MIF) has been an important prognostic factor in breast cancer by regulating tumor initiation, aggressiveness and progression." (PMID 35414025, 2022). "MIF expression is abnormally increased and supports the proliferation, migration and invasion of gastric cancer, breast cancer, lung cancer and pancreatic cancer cells." (PMID 36042480, 2022). "For example, HIF-1α regulates MIF secretion in breast cancer cells to promote tumor proliferation, angiogenesis, and metastasis." (PMID 36496973, 2022). "Taken together, these data indicate that MIF is upregulated in human breast tumors and correlates with the poor clinical outcome in breast cancer patients." (PMID 34012010, 2021). "The metabolic enzymes EZH2 and MIF connected to deregulated metabolites L-lysine and citric acid were commonly regulated in breast cancer." (PMID 34790674, 2021). "MIF overexpression is frequently observed in a variety of human cancer types, including breast cancer, pancreatic cancer and ovarian cancer." (PMID 34485124, 2021). "In another breast cancer study, levels of IL-7, IL-8, IL-13, macrophage migration inhibitory factor (MIF), and TNF-β were increased, whereas those of CTACK, G-CSF, HGF, IL-1β, and TNF-α were decreased after IORT exposure." (PMID 34641806, 2021). "Kaplan–Meier analysis (GSE1456) revealed that overall survival in breast cancer patients with high MIF expression was significantly shorter than that in patients with low MIF expression." (PMID 34012010, 2021). "To determine the clinical relevance of MIF in human cancers, we analyzed MIF mRNA expression in The Cancer Genome Atlas (TCGA) breast carcinoma dataset." (PMID 34012010, 2021). "Since we observed that MIF is overexpressed in TNBC and enhance breast cancer growth and migration in vitro and in vivo, we evaluated the anticancer potency of a small-molecule chemical inhibitor of MIF to inhibit the proliferation and progression of TNBC." (PMID 32943608, 2020). "shRNA knockdown of MIF in murine breast cancer cell lines diminished primary tumor outgrowth and dramatically reduced numbers of lung micro-metastases in immunocompetent Balb/c mice but not in immune-deficient SCID mice." (PMID 33324425, 2020). "In both the breast cancer cohort and the lung adenocarcinoma cohort, we found that high protein levels of all four factors (IL-8, PDGF-AA, Serpin E1, and MIF) were associated with significantly lower survival (p < 0.0001 and p < 0.05, respectively)." (PMID 33158447, 2020). "Experiments with the murine breast cancer cell line 4T1 have shown that overexpression of MIF promotes tumour metastasis and protects cancer cells from immunogenic cell death." (PMID 32493768, 2020). "We further evaluated the expression of MIF in breast cancer patients using publically available datasets." (PMID 32943608, 2020). "Orthotopic syngeneic TNBC mammary tumors showed reduced tumor burden in MIF KO mice compared to WT mice." (PMID 32943608, 2020). "Downregulation of miRNA-451a upregulated MIF expression and increased breast cancer cell growth, invasion, and tamoxifen sensitivity." (PMID 32403384, 2020). "In breast cancer research, regulation of MIF expression and suppression of autophagic cell death is a potent mechanism contributing to chemoresistance and tumorigenicity." (PMID 30742638, 2019). "Another study demonstrated that breast cancer cells secreted MIF and led to the recruitment of S100A8+ myeloid cells, thereby promoted tumorigenesis." (PMID 31036057, 2019). "First, TGFβ1 and IL8 had higher average expression levels in more malignant cell lines; second, MIF and VEGFA had higher average expression levels in more malignant breast cancer tissues, and the high expression levels were associated with poor survival rate." (PMID 31293831, 2019).
breast cancer (continued). "MIF is also overexpressed in various malignant tumors such as brain tumors, breast cancer, and head and neck cancer." (PMID 31284478, 2019). "The relationship between MIF and cancers such as non-small cell lung cancer, breast cancer, colorectal cancer, prostate cancer, esophageal cancer, hepatocellular carcinoma, and ovarian cancer has been investigated." (PMID 30742638, 2019). "In this study, we demonstrate that depletion of MIF expression in the 4T1 model of breast cancer strongly promotes ICD in vitro under serum-free conditions." (PMID 29864117, 2018). "For example, miR-451a was found to affect proliferation and sensitivity to tamoxifen in breast cancer via targeting of the macrophage migration inhibitory factor (MIF)." (PMID 29720118, 2018). "Using the MMTV-PyMT murine model of breast cancer, we observed that elevated MIF expression promoted tumor appearance and growth." (PMID 29864117, 2018). "We published previously that, in the 4T1 model of breast cancer, MIF expression promotes tumor growth only in a host with a fully intact immune system capable of mounting an adaptive immune response." (PMID 29864117, 2018). "We therefore moved to the more tractable 4T1 model of breast cancer to dissect the contributions of MIF to tumor growth." (PMID 29864117, 2018). "The overexpression of MIF in breast cancer cells, and its reported interaction with HSP90 and CXCR-4, is known to induce resistance to apoptosis and stimulation of proliferation via the AKT pathway." (PMID 30060564, 2018). "This leads to greater tumor control in MIF-depleted tumors, a phenotype that we show is recapitulated in a spontaneous, genetic model of breast cancer." (PMID 29864117, 2018). "Supporting this, we confirmed our previous observation that higher MIF expression supported tumor growth in the 4T1 murine model of breast cancer." (PMID 29864117, 2018). "To study the role of MIF in a syngeneic model of breast cancer, we utilized the MMTV-PyMT murine model of spontaneous breast cancer." (PMID 29864117, 2018). "The overexpression of MIF has been demonstrated in breast cancer cells, in which, through the interaction with HSP90 and CXCR-4, MIF induces resistance to the apoptosis and stimulates the proliferation via AKT pathway." (PMID 28686225, 2017). "During the invasive progression of breast cancer, MIF appears involved in the phenomena of trans-endothelial cells migration, related to the intra- and extra-vasation processes." (PMID 28686225, 2017). "There has been study shown that MIF is overexpressed in breast cancer tissues, cells, and serum of patients." (PMID 26911617, 2016). "Our date showed that VEGF-C expression reduced after reducing MIF expression in breast cancer cells MCF-7." (PMID 26911617, 2016). "To extend our observations beyond renal cancer lines, we also tested the effects of radiation exposure on MIF levels in the breast cancer cell line MCF-7 and the lung cancer line H1299." (PMID 26741693, 2016). "In vivo, genetic knock-out of MIF was shown to blunt tumor outgrowth in animal models of breast cancer, skin cancer, gastric cancer, bladder cancer, lung cancer and fibrosarcoma." (PMID 27636991, 2016). "Overexpression of MIF was reported in numerous tumors such as non-small cell lung cancer, gastric cancer, breast cancer, metastatic melanoma, and neuroblastoma." (PMID 26911617, 2016). "We selected the CXCL12 and MIF cytokines for further study because of a high fold change (more than 80-fold) and a known role in breast cancer metastasis." (PMID 26396176, 2015). "The heat-sensitive chemokines CXCL12 and MIF, both known to promote breast cancer metastasis, showed the highest fold change in secretion by irradiated lung epithelial cells compared to control, which was confirmed in our study." (PMID 26396176, 2015).
breast cancer (continued). "Once the cells arrive in the lung, increased levels of CXCL12 and MIF retain the breast cancer cells in lung and provides it with survival and growth factors, so metastatic growth is enhanced." (PMID 26396176, 2015). "MIF serum levels are elevated in breast cancer patients and MIF has been shown to be overexpressed in breast cancer tissue compared to normal breast." (PMID 24939415, 2014). "In a set of 98 serum proteins, MIF was able to discriminate normal tissue from breast cancer, although the authors considered the elevation of serum MIF more indicative of the inflammatory response to breast tumor than to the tumor itself." (PMID 24939415, 2014). "Some breast cancer cells respond to exogenous MIF by triggering a massive burst of MIF secretion suggesting auto- or paracrine regulation of MIF." (PMID 25168062, 2014). "Again in breast cancer, it was found that MIF was highly upregulated in tumours cells when they were co-cultured with macrophages." (PMID 25168062, 2014). "Consistent with our finding, a recent report showed that MIF knockdown inhibited the tumorigenicity of breast cancer cells in a tumor xenograft mouse model." (PMID 25015194, 2014). "Consistent with our results, MIF is overexpressed in other tumors, including glioblastoma and breast cancer." (PMID 25015194, 2014). "In breast cancer, MIF is expressed in both tumour cells and stromal cells, including tumour-associated macrophages." (PMID 25168062, 2014). "We showed a significant increase in serum MIF average levels in breast cancer patients compared to healthy individuals." (PMID 24939415, 2014). "A series of experiments with breast cancer cell lines and macrophage cell lines showed that MIF was a major gene product that was upregulated when breast cancer cells were cocultured with macrophages." (PMID 23673510, 2013). "MIF has previously been found to be higher in mammary tumor tissues than normal mammary gland tissue." (PMID 23202969, 2012). "MIF has been shown to promote cell proliferation and tumor angiogenesis, and over-expression of MIF has been reported in various types of cancers, including prostate tumors, breast cancer, colon carcinomas, HCCs, and glioblastoma." (PMID 21438767, 2011). "MIF has recently been shown to be up-regulated by hypoxia in several tumor cell types in vitro including breast carcinoma cells." (PMID 20727156, 2010). "This study in conjunction with prior observations by others indicates that MIF has a dual role in breast cancer." (PMID 19602265, 2009). "We first applied quantitative PCR and Western blotting to study the mRNA and protein expression levels of MIF, respectively, in various invasive and non-invasive ductal breast cancer cell lines in comparison to normal epithelial cells." (PMID 19602265, 2009). "All three studies concur in failing to see any correlations between breast cancer MIF expression levels and tumour size or histological tumour grades." (PMID 19602265, 2009). "We compared intra-tumoural MIF levels in specimens from 175 breast cancer patients with those of 35 normal breast tissues." (PMID 19602265, 2009). "The over expression of macrophage migration inhibitory factor has also been reported in various cancers, including lung cancer, breast cancers, prostate cancers, ovarian cancers, colorectal cancers, and HNSCC tumors in this study." (PMID 19602232, 2009). "We thus performed a comprehensive retrospective study correlating MIF expression levels with clinical and pathological markers relevant in breast cancer using a tissue microarray (TMA) with 175 primary invasive breast cancers and 35 normal breast tissues." (PMID 19602265, 2009). "We found that anti-MIF and anti-CD74 antibodies potently blocked breast cancer cell proliferation induced by autocrine or exogenous MIF." (PMID 19602265, 2009).
breast cancer (continued). "The strong statistical significance of these data suggests that high levels of MIF expressed in the cytosol of breast carcinoma cells are beneficial for the outcome of breast cancer." (PMID 19602265, 2009). "Bando and colleagues noticed MIF overexpression in 93 primary breast cancer tissues with MIF localizing to tumour as well as stromal cells including TAMs." (PMID 19602265, 2009). "In conjunction, these experiments showed that proliferation of both non-invasive and invasive breast cancer cells is driven by autocrine MIF action, encompassing the secretion of endogenous MIF and signalling through MIF/CD74." (PMID 19602265, 2009). "Next, we correlated MIF expression levels in primary human breast cancer with clinicopathological parameters." (PMID 19602265, 2009). "Overall, we found that MIF levels were upregulated in breast cancer tissue compared to normal breast epithelium according a semi-quantitative immunoreactivity score (Remmele and Stegner)." (PMID 19602265, 2009). "Both MDA-MB-231 and MDA-MB-468 breast cancer cells slowly secreted MIF during unstimulated cultivation." (PMID 19602265, 2009). "MIF was identified as a major gene product upregulated in breast cancer cells upon coculture with macrophages." (PMID 19602265, 2009). "The classifiers were able to distinguish normal tissue from breast cancer with a classification performance of AUC = 0.82 ± 0.04 with the proteins MIF, MMP-9, and MPO." (PMID 19476629, 2009). "Surprisingly, invasive MDA-MB-231 breast cancer cells exhibited significantly lower MIF mRNA and protein levels when compared with the non-invasive cells or MCF-12A." (PMID 19602265, 2009). "Of note, MIF levels are markedly elevated in numerous tumour entities such as prostate tumours, breast cancer, or colon carcinomas." (PMID 19602265, 2009). "We calculated the relative upregulation factors of MIF secretion (ratio of rMIF-induced MIF secretion over basal MIF secretion) in both breast cancer cell types." (PMID 19602265, 2009). "rMIF-triggered secretion of endogenous breast cancer cell-MIF is likely to encompass both a burst of preformed MIF release at 10–20 min and de novo synthesized MIF, appearing 4 h after inflammatory stimulation with rMIF." (PMID 19602265, 2009). "MIF expression in primary human breast cancers was measured by tissue microarray and a semi-quantitative immunoreactivity score (IRS) and comparison with histopathological parameters and patient outcome data." (PMID 19602265, 2009). "MIF is overexpressed in various breast cancer cell lines and human breast cancer tissue but its functional role in the pathogenesis of this tumour entity is poorly understood." (PMID 19602265, 2009). "The effect of MIF on HIF-1 activity was investigated in human breast cancer MCF-7 and MDA-MB-231 cells, and osteosarcoma Saos-2 cells." (PMID 18493321, 2008). "Ovarian and breast cancer cells had a MIF-dependent increase in angiogenic factors when co-cultured with macrophages." (PMID 17650334, 2007). "Moreover, our findings establish that WISP1 enhances metastatic plasticity in ER+ breast cancer by amplifying MIF signaling and engaging Lyn/Fyn-mediated cytoskeletal remodeling, even in low-CD74 contexts." (PMID 41597235, 2026). "Recent mechanistic insights have revealed that breast cancer stem cells (BCSCs) can secrete macrophage migration inhibitory factor (MIF), which activates the WNT/β-catenin signaling axis, subsequently upregulating MYC and its downstream effector, the glycolytic enzyme ALDOC." (PMID 40936705, 2025). "Therefore, MIF emerges as a critical regulator of metabolic reprogramming and immunosuppression in breast cancer, representing a promising therapeutic strategy to improve ICB-based immunotherapy outcomes." (PMID 40342932, 2025).